AR (androgen receptor)
Diseases named in the same sentence as AR in open-access papers (continued):
Sharing a sentence is not in itself a finding about the gene and the disease.
sexual dysfunction (9 papers, 2009 to 2025). Disturbances in sexual desire and the psychophysiologic changes that characterize the sexual response cycle and cause marked distress and interpersonal difficulty. "A meta-analysis of 17 different randomized, placebo-controlled trials of 17,494 subjects confirmed that rates of sexual dysfunction were significantly increased when using 5 AR inhibitors." (PMID 40490610, 2025). "FPN disrupted reproductive health by influencing the expression and activity of NOS and AR, leading to compromised erectile function, sexual dysfunction, and hormonal imbalance." (PMID 40423450, 2025). "The possible roles of NO/cGMP, dopamine, testosterone, and AR gene expression in maternal codeine-induced sexual dysfunction were investigated." (PMID 36099318, 2022). "In conclusion, codeine programmed sexual dysfunction by suppressing the levels of dopamine and testosterone, as well as repressing the expression of androgen receptor mRNA." (PMID 36099318, 2022). "Hence, codeine-induced sexual dysfunction may involve several pathways viz suppression of testosterone and AR, reduction of dopamine level, and downregulation of NO/cGMP signaling." (PMID 36099318, 2022). "It is apparent there are significant sexual dysfunction side effects from 5 AR inhibitors, but the data do not suggest one 5 AR inhibitor carries a higher relative risk of these side effects compared to the other." (PMID 40490610, 2025). "Our unexpected observation that percentage of AR positive stromal cells is inversely related to ASEX score, suggests that patients less able to raise AR are those with more severe side effects related to sexual dysfunction." (PMID 24959691, 2014). "Analysis of bivariate correlations between sexual dysfunction in former finasteride users as described by the ASEX score points and laboratory biomarkers continuous values highlighted that present ASEX points were inversely related to % of AR positive stromal cells (Rho = −0.722, P = 0.043)." (PMID 24959691, 2014). "Taken together, these results suggest that the decline of AR expression in the upper lumbar spinal cord may be a link in the attenuation of the GRP system after SPS exposure, and consequently contributes to the appearance of sexual dysfunctions, including erection and ejaculation difficulties." (PMID 19169356, 2009).
basal cell carcinoma (8 papers, 2011 to 2026). A carcinoma involving the basal cells. "Yet in our study, 64.2% of basal cell carcinomas and 11.5% of squamous cell carcinomas of the skin were AR positive." (PMID 38790919, 2024). "Androgen receptor expression was detected in about 80% of basal cell carcinomas." (PMID 21152127, 2011). "Immunohistochemistry revealed focally positive BerEP4, CD34-positive stroma, negative androgen receptor, and positive bcl-2, consistent with trichoblastoma and distinguishing the tumor from basal cell carcinoma." (PMID 42196849, 2026). "Compared to conventional acinar PCs, basal cell carcinoma usually shows little or no androgen receptor (AR) expression, with a very low percentage of patients or weak and patchy immunohistochemical staining reported in the literature." (PMID 35323352, 2022). "Different from basal cell carcinomas, benign trichoblastic neoplasms showed no expression of androgen receptor." (PMID 21152127, 2011).
cutaneous melanoma (8 papers, 2022 to 2026). A primary melanoma arising from atypical melanocytes in the skin. "Several studies have associated AR expression and patient survival in various cancers, yet there are limited studies examining the relationship between AR expression and cutaneous melanoma." (PMID 36833272, 2023). "In this paper, we use The Cancer Genome Atlas (TCGA) and The Cancer Proteome Atlas (TCPA) to evaluate the relationship between AR gene and AR protein expression in human cutaneous melanoma, and their association with OS in patients." (PMID 36833272, 2023). "The findings of this study suggest that a higher level of tumor AR protein is positively associated with a better overall survival in cutaneous melanoma patients, which remains true after adjusting to age of diagnosis, stage of disease, sex of patients, and Breslow depth of the tumors." (PMID 36833272, 2023). "Current literature has explored possible pathways into AR’s effects, both harmful and protective, on cutaneous melanoma development." (PMID 36833272, 2023). "We reviewed epidemiological and molecular data on sex differences in cancers of the esophagus, bladder, head and neck, lung, liver, kidney, stomach, and skin melanoma, as well as the potential role of androgens and androgen receptor (AR) activity in these cancers." (PMID 41228208, 2025). "Nonetheless, there remains a lack of complete understanding of what role AR signaling plays in most hormone-independent cancers alongside cutaneous melanoma." (PMID 36833272, 2023).
multiple myeloma (8 papers, 2015 to 2025). "Markers previously reported to be associated with metastasis aggressiveness in this patient cohort (MetA, MetB, and MetC subtypes; tumour cell proliferation index; and PSA and AR IR scores) were compared between the group with a myeloma-like pattern and the group with a non–myeloma-like pattern." (PMID 36743403, 2022). "A morphological analysis did not imply that the myeloma-like phenotype is related to previously known biological risk factors for this patient group, such as tumour cell proliferation, AR activity, bone remodelling, or the recently described metastasis subclasses MetA, MetB, and MetC." (PMID 36743403, 2022). "These new targets to be considered in multiple myeloma treatment are the NOTCHs, BCL2, the IDHs, AR, NF2, Porcupine, the JAKs, MEK1/2 and the Aurora kinases." (PMID 31523388, 2019). "The prognostic value of the myeloma-like metastatic pattern was compared with the following markers previously reported to be of prognostic relevance in this patient cohort: the molecular metastasis subtypes MetA, MetB, and MetC; tumour cell proliferation index; PSA and AR IR scores; and KPS." (PMID 36743403, 2022). "We hypothesized our novel finding of down-regulated AR and AR-V expression following JQ1 treatment represented an important component of the JQ1 anti-AR mechanism of action, reminiscent of down-regulated MYC expression in multiple myeloma cells." (PMID 25908785, 2015).
preeclampsia (8 papers, 2014 to 2023). Preeclampsia is a hypertensive disorder of pregnancy that is characterized by new-onset hypertension with proteinuria presenting after 20 weeks of gestation, and depending on mild or severe forms may initially present with severe headache, visual disturbances, and hyperreflexia. "Circulating testosterone levels in women with preeclampsia are elevated 2–3 fold, and preeclampsia is associated with elevated placental AR expression." (PMID 37626712, 2023). "Preeclampsia is also associated with elevated placental androgen receptor (AR) gene expression." (PMID 30325182, 2018). "In human placenta, AR was found mainly in the syncytiotrophoblasts and stromal cells, and increased AR expression might be a possible mechanism for its association with preeclampsia." (PMID 27149376, 2016). "Mutations in AR are correlated with increased risk for the development of preeclampsia." (PMID 25675430, 2015). "Also, genetic polymorphisms in the AR gene are associated with increased risk of preeclampsia." (PMID 30325182, 2018). "The most relevant targets for preeclampsia were: AR, VDR, SLC6A2, NOS3 and CHRM4, while ABCG2, ERBB2, CES1 and REN led to the most relevant off-targets." (PMID 33546161, 2021). "Taken together, these data strongly implicate AR-mediated testosterone action as an important pathway contributing to clinical manifestation of preeclampsia." (PMID 30325182, 2018). "Multiple studies have also shown that maternal plasma testosterone is increased in cases of severe preeclampsia, with placentas from preeclamptic pregnancies expressing increased syncytiotrophoblast and stromal cell expression of AR." (PMID 25675430, 2015). "Women with preeclampsia have elevated androgen levels and AR gene expression, and it has been hypothesized that androgens affect vascular function and that vascular smooth muscle is involved in the development of preeclampsia." (PMID 37626712, 2023). "Women with preeclampsia have elevated androgen levels and AR gene expression, and it has been hypothesized that androgens affect vascular function, and vascular smooth muscle is involved in the development of preeclampsia." (PMID 34357016, 2021). "Cord blood had a decreased level of DHEAS in the preeclampsia group, but the two groups had similar levels of P4, E2, and T. The two groups had similar placental mRNA levels of ERα, ERβ, AR, and PR, but the preeclampsia group had a higher level of ERβ protein and a lower level of ERα protein." (PMID 32070380, 2020). "In addition, testosterone and its receptor, androgen receptor, are expressed at increased level in preeclampsia." (PMID 25392996, 2014). "The analysis of the final models points toward a relevance of AR, VDR, SLC6A2, NOS3 and CHRM4 as targets for preeclampsia." (PMID 33546161, 2021).
salivary gland tumors (8 papers, 2017 to 2025). "A case series of patients with salivary gland tumors reported an overall response rate of 64.7%, including three complete clinical responses, with combined androgen blockage and inhibition of androgen receptor signaling for salivary gland tumors." (PMID 31428578, 2019). "A rich literature documented the expression and the role of AR in salivary glands tumors." (PMID 29385707, 2018). "In salivary gland tumors (SGTs), little and conflicting information about the role of the estrogen receptor alpha (ERα), progesterone receptor (PgR) and androgen receptor (AR) has been described and in most cases the use of sex hormone antagonists is not contemplated in clinical practice." (PMID 29385707, 2018).
acinar adenocarcinoma (7 papers, 2017 to 2025). "Luminal cells of the acini are considered the most common cell of origin for PCa, with acinar adenocarcinoma expressing androgen receptor (AR) accounting for ∼95 % of PCa cases." (PMID 39033689, 2024). "The most commonly reported PCa is acinar adenocarcinoma, which is androgen receptor (AR)-positive and arises from the prostate gland secretory luminal cell lineage." (PMID 31018586, 2019). "Adenocarcinoma, not otherwise specified (AC NOS) and acinic cell carcinoma (AcCC) are AR-positive in 26% and 15% of the cases, respectively." (PMID 28208703, 2017).
autoimmune disease (7 papers, 2018 to 2024). A disorder resulting from loss of function or tissue destruction of an organ or multiple organs, arising from humoral or cellular immune responses of the individual to their own tissue constituents. "Taken together, the data from clinical studies as well as the results generated in these B cell-deficient mouse models suggest that AR may be a plausible target for new therapies to treat autoimmune diseases, such as RA." (PMID 38579776, 2024). "We included 844 CRPC patients receiving AR-directed therapies, of whom 36 (4.3%) had autoimmune diseases and 47 (5.6%) second tumors as comorbidities." (PMID 32580478, 2020). "However, AR can be destabilized by Celastrol and result in the regulation of peripheral T cell proliferation and Th1 differentiation to inhibit autoimmune diseases." (PMID 35309340, 2022). "Blockage of AR activity by the AR antagonist flutamide, attenuated the protection from insulitis, autoantibody production, metabolome changes, and the capacity of T cell transfer to confer autoimmune disease in NOD SCID mice." (PMID 29662485, 2018). "In this review, we will discuss how androgens and the expression of functional androgen receptor affect immune cells and how this may dampen or alter immune response(s) and affect autoimmune disease incidences and progression." (PMID 29755457, 2018). "One study investigating sexual dimorphism in autoimmune disorders utilised mouse models and demonstrated that DHT treatment may have a protective effect against autoimmunity due to AR-dependent upregulation of Aire mRNA expression in thymic stromal cells." (PMID 38579776, 2024). "Furthermore, in the context of some autoimmune diseases such as rheumatoid arthritis, women with lower number of CAG repeats in the androgen receptor gene, that confers higher androgen sensitivity, develop a more severe clinical course." (PMID 34731444, 2022).
Autoimmunity (7 papers, 2014 to 2024). The occurrence of an immune reaction against the organism's own cells or tissues. "It would therefore be interesting to determine whether this procedure can also correct organ-related autoimmunity in patients with AR partial RelB deficiency." (PMID 39231201, 2024). "Humoral autoimmunity in lupus extends to loss of tolerance for a wide variety of autoantigens, and we investigated whether the AR CAG repeat length might be related to differences in the breadth of the autoimmune response as well." (PMID 24711544, 2014). "Androgen binds to the androgen receptor (AR) to regulate gene expression, but how androgen protects against autoimmunity is not well understood." (PMID 27072778, 2016). "Androgen/androgen receptor complexes can directly induce anti-inflammatory IL-10 expression by CD4 + T cells, which has been proposed to underlie male protection from central nervous system (CNS) autoimmunity." (PMID 34930155, 2021). "Deciphering whether the thymic epithelium is a target compartment for androgen/AR-mediated regulation of inflammation and autoimmunity, and defining the mechanisms mediating such effects, will be important tasks for future studies." (PMID 32714327, 2020). "Once the AR target cell for BAFF regulation is identified, a knockout of the AR specifically in this cell type may be a useful approach to address if AR signalling affects autoimmunity via BAFF regulation." (PMID 29802242, 2018).
brain tumor (7 papers, 2012 to 2025). "However, IHC staining on both mouse and human brain tumor specimens demonstrated nearly 100% nuclear localization of AR but more cytosol dominant distribution pattern after enzalutamide treatment in vivo." (PMID 34094902, 2021). "Out of 19 PTEN-controlled TFs (AR is removed from our analysis to prevent bias toward prostate), we were able to derive 16, 15 and 16 TFAs from human prostate, breast and brain tumor datasets, respectively, based on the availability of their target gene expression values in the datasets." (PMID 22347425, 2012).
breast adenocarcinoma (7 papers, 2006 to 2022). "Taken together, these data show that androgen ablation cooperates with ionizing radiation to decrease tumour cell growth and survival in AR-positive breast adenocarcinomas." (PMID 27109210, 2016). "We tested the capacity of p,p'-DDE to stimulate the proliferation of CAMA-1 cells, a human breast adenocarcinoma cell line that expresses both the ERα and the AR." (PMID 18275596, 2008). "Two cases (1 female and 1 male) showed positive immunoreactivity for AR in nuclei in the tumors initially selected in the non-mammary adenocarcinoma group." (PMID 17020615, 2006). "Elevated AR is also present in 9% of breast adenocarcinoma (BRCA)." (PMID 30053901, 2018). "By studying a large number of cancer types, we found that genetic correlates in any single cancer type can be found in other cancer types as well (for example, Nrf2 activation in LUSC, LUAD and hepatobiliary cancer and AR expression in prostate and breast adenocarcinomas)." (PMID 27109210, 2016). "These two mouse mammary adenocarcinoma cell lines were generated by stable transfection of a green fluorescent protein (GFP) tagged AR (pTRE-Tight-GFP-AR) or GR (pTet-nGFP-C656G) construct under tetracycline repressible promoter into the same parental cell line (3134 cells)." (PMID 25133404, 2014).
carcinoma in situ (7 papers, 2010 to 2025). "AR gene maps to the X-chromosome, and X-chromosome polysomy, as well as an AR gene copy number increase, were emphasized in most invasive MBCs and in situ carcinomas." (PMID 38612922, 2024). "CRISP3 belongs to a large family of cysteine-rich secretory proteins and is essential for the development of invasive PCa in vivo from carcinoma in situ as well as for AR-independent transcriptional processes." (PMID 37188204, 2023). "AR monosomy was also present, even if at lower levels, in in situ carcinoma." (PMID 33534004, 2021). "AR was clearly expressed in an in situ carcinoma and an adenocarcinoma and showed a heterogeneous expression pattern in these lesions in comparison with the normal control prostate, with some cells showing absent or very low AR staining." (PMID 20663219, 2010).
Ewing sarcoma (7 papers, 2017 to 2024). A small round cell tumor that lacks morphologic, immunohistochemical, and electron microscopic evidence of neuroectodermal differentiation. "Expression of NR3C1 and AR was higher in DSRCT PDXs as compared to Ewing sarcoma and CIC-DUX4 PDXs." (PMID 38575753, 2024). "It is unclear if the cell of origin for Ewing sarcoma would express AR." (PMID 34409300, 2021). "High AR expression could present as a potential therapeutic target for DSRCT while taxanes may be more effective in Ewing sarcoma compared to DSRCT based on TUBB3 expression." (PMID 29225486, 2017). "Further, AR signaling promoted increased R-loop formation in the EWSR1 gene and drove chromosomal breakage at high frequency at the same genomic locus that is rearranged in Ewing sarcoma." (PMID 34409300, 2021).
Intellectual disability (7 papers, 2018 to 2024). "ERLIN2 mutation as causative of SPG18 was first mapped in an AR Turkish family with early onset intellectual disability, motor impairment, and multiple joint contractures in 2011." (PMID 38427163, 2024). "Interestingly, AR targets that were differentially expressed in male pups prenatally exposed to BPA were significantly associated with “autism spectrum disorder or intellectual disability” (p value = 1.04E−07) and “pervasive developmental disorder” (p value = 1.42E−04)." (PMID 36803626, 2023). "Gene ontology analysis by IPA software revealed that transcriptional targets of AR, KDM5B, and SMAD4 that were differentially expressed in response to BPA treatment were significantly associated with “autism spectrum disorder or intellectual disability”." (PMID 36803626, 2023). "These genes encoded the androgen receptor (AR), insulin receptor (INSR), alpha-thalassemia/mental retardation, X-linked (ATRX) chromatin remodeler, and the patched protein homolog (PTCH1) involved in the Hedgehog pathway (Hh) for bone development and chondrocyte differentiation." (PMID 37760551, 2023). "In addition to AR targets, KDM5B targets dysregulated in male and female pups, and SMAD4 targets dysregulated in male pups were also significantly associated with “autism spectrum disorder or intellectual disability”." (PMID 36803626, 2023).